ZNF573 (zinc finger protein 573)
Description:
May be involved in transcriptional regulation.
Synonyms: FLJ30921
Tractability: PROTAC: ubiquitination databases record sites on it.
Gene: Protein-coding gene on chromosome 19 (37,735,833 to 37,817,300, reverse strand). Ensembl gene ENSG00000189144.
Subcellular location: Nucleus
Subcellular location (Human Protein Atlas): Intermediate filaments; Cytosol
Pathways (Reactome):
Gene expression (Transcription): Generic Transcription Pathway
Gene Ontology:
Molecular function: DNA-binding transcription factor activity, RNA polymerase II-specific; RNA polymerase II cis-regulatory region sequence-specific DNA binding
Biological process: regulation of transcription by RNA polymerase II; regulation of DNA-templated transcription
Cellular component: nucleus; nucleoplasm
Genetic constraint (gnomAD): Loss-of-function variants: 39 observed, 55.39 expected, observed/expected ratio (o/e) 0.7, 90% interval 0.54 to 0.92. The upper end of that interval is the gene's LOEUF score, 0.92, which puts it in group 3 of 6, group 1 being the genes least tolerant of losing a copy. Missense variants: 706 observed, 797.6 expected, observed/expected ratio (o/e) 0.89, 90% interval 0.83 to 0.94. Synonymous variants: 236 observed, 262.13 expected, observed/expected ratio (o/e) 0.9, 90% interval 0.81 to 1.
Homologues: Orthologues: chimpanzee ZNF573 (99% identical), macaque ZNF573 (96% identical), guinea pig ZNF573 (74% identical). Paralogues in human: ZNF30 (48% identical), ZNF546 (47% identical), ZNF540 (46% identical), ZNF571 (44% identical), ZNF658 (44% identical), ZNF841 (43% identical), ZNF836 (43% identical), ZNF585B (43% identical), ZFP14 (42% identical), ZNF33B (42% identical), ZNF528 (42% identical), ZFP82 (41% identical), and 164 more.
Diseases named in the same sentence as ZNF573 in open-access papers:
ZNF573 is named in the same sentence as 9 diseases in open-access papers, as found by Europe PMC text mining. Sharing a sentence is not in itself a finding about the gene and the disease. The quoted sentences say what the papers report.
ovarian cancer (3 papers, 2022 to 2025). A primary or metastatic malignant neoplasm involving the ovary. "According to previous clinical studies, the expression level of ZNF573 protein in the serum of patients with ovarian malignant tumors was significantly higher than that of patients with benign ovarian tumors and healthy individuals." (PMID 34995016, 2022). "Although there is no data on ZNF573 and EC, it appears to have a diagnostic role for ovarian cancer in combination with other biomarkers." (PMID 40871563, 2025).
cervical cancer (2 papers, 2022 to 2023). A primary or metastatic malignant neoplasm involving the cervix. "The function of ZNF573 is still undetermined, and only a recent study has suggested that ZNF573 may be involved in cervical cancer activating the cancer progression through the regulation of transcription or structural integrity of cells." (PMID 36672361, 2023). "After quantitative calculation, the levels of serum CCL18 and CXCL1 antigens, and C1D, TM4SF1, FXR1, and ZNF573 IgG autoantibodies were significantly higher in patients with OC than in those with cervical cancer, liver cancer, breast cancer, gynecological benign tumor patients, and healthy women." (PMID 34995016, 2022).
influenza (1 paper, 2015). An acute viral infection of the respiratory tract, occurring in isolated cases, in epidemics, or in pandemics; it is caused by serologically different strains of viruses (influenzaviruses) designated A, B, and C, has a 3-day incubation period, and usually lasts for 3 to 10 days. "We cloned the coding region of hGATAD1 tagged with the human influenza haematogglutinin epitope (HA) or human ZNF573-tagged with both MYC and FLAG epitopes into a lentivirus vector (LV) that expressed GFP." (PMID 26671628, 2015).
cancer (2 papers, 2022 to 2023). A tumor composed of atypical neoplastic, often pleomorphic cells that invade other tissues. "In summary, combined detection of CCL18 and CXCL1 chemokines, and C1D, TM4SF1, FXR1, and ZNF573 autoantibodies can improve the specificity and sensitivity of OC diagnosis, and its diagnostic efficiency is higher than that of other malignant tumors." (PMID 34995016, 2022).
ZNF573 also shares sentences with these, for which no sentence is quoted: benign ovarian tumors (1 paper); breast carcinoma (1); gynecological benign tumor (1); liver cancer (1); lung carcinoma (1).